KRT13 (keratin 13)
Description:
Structural component of intermediate filaments in mucosal stratified squamous epithelia. Forms heteropolymers with the type II keratin KRT4, assembling into keratin intermediate filament networks that provides structural integrity and mechanical stability of the mucosal epithelium. Contributes to postnatal tongue mucosal cell homeostasis and tissue organization in response to mechanical stress, potentially through regulation of the G1/S phase cyclins CCNE1 and CCNE2 (By similarity).
Synonyms: K13; CK13; MGC3781; MGC161462; WSN2
Tractability: PROTAC: ubiquitination databases record sites on it.
Gene: Protein-coding gene on chromosome 17 (41,500,981 to 41,505,705, reverse strand). Ensembl gene ENSG00000171401.
Subcellular location (Human Protein Atlas): Intermediate filaments
Pathways (Reactome):
Developmental Biology: Formation of the cornified envelope; Keratinization
Gene Ontology:
Molecular function: protein binding; structural constituent of skin epidermis; structural molecule activity
Biological process: cytoskeleton organization; epithelial cell differentiation; intermediate filament organization; morphogenesis of an epithelium; regulation of translation in response to stress
Cellular component: extracellular exosome; intermediate filament cytoskeleton; keratin filament; nucleus; cytoskeleton; cytosol
Genetic constraint (gnomAD): Loss-of-function variants: 27 observed, 41.15 expected, observed/expected ratio (o/e) 0.66, 90% interval 0.48 to 0.9. The upper end of that interval is the gene's LOEUF score, 0.9, which puts it in group 3 of 6, group 1 being the genes least tolerant of losing a copy. Missense variants: 605 observed, 627.45 expected, observed/expected ratio (o/e) 0.96, 90% interval 0.9 to 1.03. Synonymous variants: 266 observed, 247.77 expected, observed/expected ratio (o/e) 1.07, 90% interval 0.97 to 1.19.
Homologues: Orthologues: chimpanzee KRT13 (99% identical), tropical clawed frog krt15.2 (50% identical), tropical clawed frog krt15 (47% identical). Paralogues in human: KRT15 (73% identical), KRT14 (61% identical), KRT16 (61% identical), KRT10 (56% identical), KRT17 (56% identical), KRT19 (55% identical), KRT24 (54% identical), KRT12 (53% identical), KRT9 (50% identical), KRT27 (48% identical), KRT28 (46% identical), KRT26 (45% identical), and 56 more.
Diseases named in the same sentence as KRT13 in open-access papers:
KRT13 is named in the same sentence as 80 diseases in open-access papers, as found by Europe PMC text mining. Sharing a sentence is not in itself a finding about the gene and the disease. The quoted sentences say what the papers report.
cervical cancer (12 papers, 2016 to 2025). A primary or metastatic malignant neoplasm involving the cervix. "A previous study showed the potential biological function of NSUN2, a regulator of m5C, in common gynaecological cancers, where NSUN2 promotes cervical cancer cell migration and invasion by causing m5C methylation of keratin 13 (KRT13) transcripts." (PMID 37042849, 2023). "The m5C regulator NSUN2 promoted cervical cancer cell migration and invasion by inducing m5C methylation of keratin 13 (KRT13) transcripts." (PMID 38655053, 2024). "KRT13 expression is decreased in oral and cervical cancer tissue, and the gene is epigenetically silenced in an oral squamous cell carcinoma cell line and in invasive bladder cancer tissue." (PMID 36610719, 2023). "Next, we verified expression of these genes in the other cervical cancer cell line, SiHa, and found that only KRT13 levels displayed significant downregulation in NSUN2-depleted SiHa cells as well." (PMID 35280737, 2022). "In contrast, NSUN2 played a robust role for tumorigenesis in cervical cancer via promoting m5C modification on KRT13 transcripts, which were then recognized and stabilized by an m5C reader protein YBX1." (PMID 35280737, 2022). "We identified keratin 13 (KRT13) mRNA as the downstream target gene of NSUN2 in cervical cancer, which contributes to the activity of tumor cell migration and invasion." (PMID 35280737, 2022). "In this study, we not only demonstrated the ability of KRT13 to stimulate cervical cancer cell migration and invasion, but also revealed a novel upstream NSUN2-m5C-YBX1 pathway for regulation of KRT13 mRNA stability and expression." (PMID 35280737, 2022). "Collectively, our results demonstrated that NSUN2 promotes cervical cancer cell migration and invasion via a KRT13-dependent manner." (PMID 35280737, 2022). "A set of key risk factors anaerococcus, hydrogenophilaceae, eubacterium, PSMB10, KCNIP1 and KRT13 have been identified, which are thought to be involved in the regulation of viral response, cell cycle and epithelial cell differentiation in cervical cancer." (PMID 29745858, 2018). "Furthermore, besides mRNA levels, the expression of KRT13 protein was also obviously downregulated in NSUN2 knockdown CaSki and SiHa cells, suggesting KRT13 mRNA as the downstream target gene of NSUN2-m5C regulatory pathway in cervical cancer cells." (PMID 35280737, 2022). "In cervical cancer, NSUN2 promotes m5C modification on KRT13, and m5C-methylated KRT13 is recognized and stabilized by the m5C reader protein YBX1." (PMID 41462962, 2025). "Mechanistically, YBX1 recognises NSUN2‐induced m5C methylation of keratin 13 (KRT13) transcripts, enabling its stable expression and ultimately promoting cervical cancer survivability." (PMID 38572667, 2024). "In the present study, we focused on KRT13 as a candidate radioresistance gene because certain keratins (KRTs) are reportedly shown to have cancer stem-like properties, including KRT19 in hepatocellular carcinoma and colorectal cancer, KRT6 in lung cancer and KRT17 in cervical cancer." (PMID 36610719, 2023).
squamous cell carcinoma (10 papers, 2009 to 2024). A carcinoma arising from squamous epithelial cells. "Gradual loss of KRT13 expression in oral mucosa is linked to dysplastic transformation and squamous cell carcinoma." (PMID 27711225, 2016). "Notably, a recent study showed that enhanced KRT13 expression is associated with radioresistance in squamous carcinoma cells, consistent with our current finding in pancreatic cancer." (PMID 36610719, 2023). "During preparation of this manuscript, other investigators reported that KRT13 promotes the stemness of breast cancer cells and KRT13 is associated with radioresistance and stemness in squamous cell carcinoma cells, which further emphasized the importance of KRT13 in cancer stem cells." (PMID 36610719, 2023). "Reduced KRT13 expression is observed in oral dysplasia, squamous cell carcinomas, and carcinomas in situ." (PMID 38392212, 2024). "For instance, enhanced KRT13 gene expression bestows radiation resistance in squamous cell carcinoma cells." (PMID 36072430, 2022). "In the development of oral squamous cell carcinoma and squamous cell carcinoma of mobile tongues, a decrease in the expression of KRT4 and KRT13 has been shown." (PMID 38540309, 2024). "In cancer, KRT13 expression is found in well-differentiated urothelial carcinoma (poorly differentiated tumors were negative for KRT13), 10% of squamous carcinomas, and Brenner’s tumors." (PMID 27711225, 2016).
oral squamous cell carcinoma (9 papers, 2012 to 2024). "Keratin 13 (KRT13) belongs to the type I keratin family and its reduced expression has been associated with oral squamous cell carcinoma lesions and bladder cancer." (PMID 35267445, 2022). "KRT13 is known to be downregulated in patients with active oral squamous cell carcinoma as compared to dysplasia or normal mucosa." (PMID 35433484, 2022). "The utility of KRT13 as a marker in this study may be due to the possibility that less differentiated and more malignant cells in oral squamous cell carcinoma are responsible for lung metastasis." (PMID 38114532, 2023). "Although the loss of keratin 13 (KRT13) is reportedly linked to malignant transformation of oral epithelial cells, the molecular mechanisms through which KRT13 is repressed in oral squamous cell carcinoma (OSCC) remain unclear." (PMID 25527207, 2014).
bladder cancer (8 papers, 2010 to 2023). "That is to say, lower expressions of IGF2, GDF15, and KRT13 was associated with lower cell proliferation, invasion, and tumorigenesis of bladder cancer." (PMID 32695477, 2020). "Methylation of HOXB2, FRZB and KRT13 is independently associated with high grade disease in non-invasive bladder cancer." (PMID 20808801, 2010). "The methylation of HOXB2, FRZB, and KRT13 was greater in invasive bladder cancers as compared to non-invasive bladder cancers." (PMID 37627900, 2023). "Some studies found that KRT13 serves as a tumor suppressor with low expression in oral dysplasia, esophageal squamous cell carcinoma, bladder cancer, and so on." (PMID 35280737, 2022). "Pyrosequencing was performed to determine the methylation status of HOXB2, FRZB, and KRT13 in bladder cancer cell lines HTB-9 and UM-UC3." (PMID 20808801, 2010). "HOXB2, FRZB, and KRT13 methylation status may be potential prognostic biomarkers to predict the likelihood of getting high grade non-invasive bladder cancer, that can subsequently be used to predict tumor recurrence or progression to muscle-invasion." (PMID 37627900, 2023). "In non-invasive bladder cancers, a significantly greater extent of HOXB2, FRZB, and KRT13 methylation was detected in grade 3 tumors as compared to grade 1 and 2 tumors." (PMID 37627900, 2023). "We identified and confirmed that increased promoter methylation of HOXB2 is significantly and independently associated with invasive bladder cancer and methylation of HOXB2, KRT13 and FRZB together significantly predict high-grade non-invasive disease." (PMID 20808801, 2010). "Interestingly, the decrease in levels of protein biomarkers, including adipocyte-type fatty acid-binding protein (aFABP), glutathione S-transferase μ (GST μ), and 15-hydroxyprostaglandin dehydrogenase (PGDH), as well as cytokeratin 13 (CK13), has been described in high-grade human bladder cancer." (PMID 29396722, 2018).
breast carcinoma (8 papers, 2016 to 2023). "KRT13 up-regulation in primary breast cancer was associated with decreased overall patient survival." (PMID 35078507, 2022). "Breast cancer brain metastases upregulate KRT13 and downregulate CCDC8, and these genes were differentially expressed in the primary and metastatic samples." (PMID 37138793, 2023). "The function and mechanisms of KRT13 in breast cancer progression and metastasis were assessed by overexpression and knockdown followed by examination of altered behaviors in breast cancer cells and in xenograft tumor formation in mouse mammary fat pad." (PMID 35078507, 2022). "The role is particularly relevant to breast cancer treatment, because KRT13 is a target gene of estrogen receptor α activation, while both estrogen and tamoxifen behave as antagonists of the KRT13 gene." (PMID 35078507, 2022). "Overexpression of KRT13 markedly enhanced breast cancer cell growth, migration, and invasion in vitro and promoted tumorigenesis and metastasis in athymic mice." (PMID 35078507, 2022). "Human breast cancer specimens were examined by immunohistochemistry and multiplexed quantum dot labeling analysis to correlate KRT13 expression to breast cancer progression and metastasis." (PMID 35078507, 2022). "KRT13 expression in metastatic specimens (12/21) was significantly higher than in the primary breast cancer (13/41)." (PMID 35078507, 2022). "Results from these analyses suggest that c-Myc is a key KRT13 downstream mediator promoting aggressive behavior and stem cell-like properties in breast cancer cells." (PMID 35078507, 2022). "This probability was further strengthened by single cell mQDL staining of clinical breast cancer tissues, which demonstrated that KRT13 expression was inversely correlated with PG, which was inversely correlated with c-Myc." (PMID 35078507, 2022). "In this study, we explored the mechanism by which KRT13 promotes breast cancer progression and metastasis." (PMID 35078507, 2022). "Here, we manipulated c-Myc expression in KRT13-overexpressing and KRT13-knockdown breast cancer cells." (PMID 35078507, 2022). "In this study, KRT13 induced stem cell phenotypes in MCF7 breast cancer cells, and increased expression of stemness-related genes of CD44, c-Myc, ALDH1A1 and Nanog." (PMID 35078507, 2022). "In this study, we investigated the potential role of KRT13 in breast cancer using cell lines that expressed low (MCF7) or high endogenous KRT13." (PMID 35078507, 2022). "KRT13 expression in 58 human breast cancer tissues was up-regulated especially at the invasive front and in metastatic specimens (12/18) (p < 0.05)." (PMID 35078507, 2022). "KRT13 also promotes stemness and drives metastasis in breast cancer through a plakoglobin/c-Myc signaling pathway." (PMID 36072430, 2022). "We determined KRT13 expression in 41 primary and 21 metastatic breast cancer tissue specimens by IHC." (PMID 35078507, 2022). "KRT13 promoted the CD44+CD24− phenotype, a combination of breast cancer stem cell markers associated with invasion and poor prognosis." (PMID 35078507, 2022). "KRT13-positive cancer cells were detected at the invasive front of breast cancer as well as prostate cancer." (PMID 35078507, 2022). "The objective of this study is to elucidate the mechanism by which KRT13 promotes breast cancer growth and metastasis." (PMID 35078507, 2022). "This study reveals that KRT13 promotes breast cancer cell growth and metastasis via a plakoglobin/c-Myc pathway." (PMID 35078507, 2022). "Overexpression of KRT13 led to increased breast cancer cell proliferation, migration and invasion in vitro, and tumor formation and metastasis in vivo, while knockdown of KRT13 resulted in alleviating effects in vitro and in vivo." (PMID 35078507, 2022). "On the contrary, keratin 13 expression was decreasing after knockdown of vimentin in breast cancer cell lines." (PMID 30005669, 2018).
breast carcinoma (continued). "In this study, we obtained results indicating that KRT13 did not affect RANKL, RANK, or OPG levels in breast cancer cells, suggesting that KRT13-induced breast cancer progression and metastasis may be regulated by a RANKL-independent mechanism." (PMID 35078507, 2022). "Keratin 13 (KRT13) plays an important role in breast cancer progression and metastasis." (PMID 35078507, 2022). "KRT13 expression was elevated in bone, brain, and soft tissue metastatic prostate cancer cell lines and in primary and metastatic clinical prostate, lung, and breast cancer specimens." (PMID 27835867, 2016). "Finally, KRT14, a closely related KRT family of KRT13, was shown to be expressed in leader cells that participated in collective invasion of breast cancer metastasis." (PMID 27835867, 2016). "Co-incidentally, the expression of neuromimicry genes including CgA and NSE, elevated in prostate cancer KRT13-overexpresing cells, was not elevated in breast cancer MCF7-KRT13 cells." (PMID 35078507, 2022). "On the other hand, it was surprising that KRT13-overexpression in prostate cancer cells elicited both bone and brain metastases, while no brain dissemination was detected in the breast cancer mouse model in this study, even following intracardiac inoculation." (PMID 35078507, 2022).
White sponge nevus (7 papers, 2011 to 2024). Any hereditary mucosal leukokeratosis in which the cause of the disease is a mutation in the KRT4 gene. "As shown in the results of previous studies, the genetic effect of KRT4 and KRT13 mutations, a member of the keratin family, is mainly implicated in the pathogenesis of white sponge nevus (WSN) disorder, a rare autosomal dominant disorder in oral mucosa." (PMID 35456240, 2022). "CK13 is required for healthy oral epithelium, and germline loss-of-function mutations in the KRT13 gene cause white sponge nevus, a rare genetic disorder that is mainly characterized by the presence of soft, white, spongy plaques in the oral mucosa." (PMID 31896811, 2020). "We report a novel KRT13 germ line variant that causes white sponge nevus (WSN) with mucosal dysplasia." (PMID 28878914, 2017). "KRT13 mutations are associated with the development of White Sponge Nevus, a condition characterized by thick white oral lesions." (PMID 27711225, 2016). "White Sponge Nevus (WSN) is traditionally considered a benign genetic disorder affecting the oral mucosa, primarily caused by pathogenic mutations in keratin 4 (KRT4) or keratin 13 (KRT13)." (PMID 38773401, 2024).